BRCA2 (BRCA2 DNA repair associated)
Diseases named in the same sentence as BRCA2 in open-access papers (continued):
Sharing a sentence is not in itself a finding about the gene and the disease.
ovarian carcinoma (continued). "Contrariwise, it has been recently shown that breast and ovarian cancer risks differ depending on the position and the type of BRCA1 and BRCA2 mutations meaning challenges regarding their structure and function." (PMID 34456966, 2021). "The most important genetic causes of ovarian cancer are mutations in BRCA1 and BRCA2 genes, which account for up to 15% of all cases." (PMID 33670479, 2021). "BRCA1 and BRCA2 are tumor suppressor genes with pivotal roles in the development of breast and ovarian cancers." (PMID 34070674, 2021). "Considerable advancements in molecular biology and therapeutics have been made in the 25 years following the discovery of tumor suppressor genes BRCA1 and BRCA2 and their roles in the development of breast and ovarian cancer." (PMID 34070674, 2021). "In 54 families with breast/ovarian cancer, three truncation mutations in the BRCA1 gene and five in the BRCA2 gene were found." (PMID 34202525, 2021). "Among 113 patients with strong family history for breast/ovarian cancer (HBOC), 18 (15.9%) were positive for heterozygous BRCA mutations (9 in BRCA1 and 9 in BRCA2)." (PMID 33726785, 2021). "Among patients with ovarian cancer, 8% have BRCA1 mutation, 6% have BRCA2 mutations, 6% have somatic BRCA1/2 mutations, and 10% have BRCA1 promoter inactivation." (PMID 33910165, 2021). "The high-risk population in ovarian cancer are those with known genetic mutation such as BRCA1 and BRCA2 and those with known history of early-onset ovarian cancer in first degree relatives." (PMID 33477343, 2021). "Many existing software packages are limited to estimating risks based on mutations in well-known cancer-related genes, such as BRCA1 and BRCA2 in breast and ovarian cancer." (PMID 34406119, 2021). "The BOADICEA model was originally developed to predict the risks of developing breast and ovarian cancer on the basis of BRCA1 and BRCA2 mutations and explicit cancer family history." (PMID 34199804, 2021). "In 23 ovarian cancer patients with detectable P/LP variants, BRCA1 and BRCA2 accounted for 13 (56.5%) patients." (PMID 33649982, 2021). "In contrast, in the ovarian cancer dataset, most of the deregulations in functional gene sets were associated with somatic BRCA1 and germline BRCA2 mutations." (PMID 33525353, 2021). "We recommend that in Poland all women with ovarian cancer and first-degree female relatives should be tested for the panel of 18 founder mutations in BRCA1, BRCA2, PALB2, and RAD51C." (PMID 33670479, 2021). "For example, prophylactic mastectomy and prophylactic oophorectomy have been proven to be effective in preventing most breast and ovarian cancer in BRCA1‐ and BRCA2‐associated hereditary breast and ovarian cancer syndrome (Petrucelli, Daly, & Pal, 2016)." (PMID 33350578, 2021). "HBOC is caused by germline mutations mainly in the BRCA1 and BRCA2 genes; individuals with HBOC tend to have early onset of breast and/or ovarian cancer as well as some other types of cancer." (PMID 35070997, 2021). "PVs in BRCA1 or BRCA2 were identified in 2.4% of all tested women but in 6.1% of women with a history of ovarian cancer (~ 2.5-fold increase)." (PMID 33926482, 2021). "For ovarian cancer, mutations in the homologous recombination (HR) repair genes BRCA1 and BRCA2 are the most common alterations and inhibitions of the DDR pathway protein poly(ADP ribose) polymerase (PARP)." (PMID 34712221, 2021).
ovarian carcinoma (continued). "Given the poor prognosis associated with this disease, identifying PVs in genes that confer an increased risk for ovarian cancer outside of BRCA1 and BRCA2 is critical for appropriate patient management." (PMID 33926482, 2021). "One study identified genes from RNA-sequencing data with potential synthetic lethal interactions with BRCA2 in ovarian cancer." (PMID 34287743, 2021). "BRCA2 and BRCA1 PTVs were associated with an increased burden of small somatic deletions, tandem duplications, and templated insertions in breast and ovarian cancers as well as other tumors like adenocarcinomas of the prostate and pancreas." (PMID 34097189, 2021). "Epithelial ovarian cancer accounts for 85–90% of all ovarian cancers and is the most common type of ovarian cancer with unique genomic characteristics such as mutations in BRCA1 and BRCA2 that encode proteins involved in DNA damaged repair." (PMID 34631788, 2021). "An important factor that contributes to ovarian cancer susceptibility is mainly represented in BRCA1 and BRCA2 genes that are associated with different risks of developing breast and ovarian cancers." (PMID 34930165, 2021). "Taken together, these results indicate significant variability of transcriptomic programs in breast and ovarian cancers associated with germline and somatic mutations in BRCA1 and BRCA2 genes." (PMID 33525353, 2021). "Germline mutations in BRCA1 and BRCA2 genes occur in up to 18% of patients with high-grade serous ovarian carcinomas (HGSOC), which are responsible for the vast majority of ovarian cancer deaths." (PMID 34202525, 2021). "HBOC is associated with pathogenic variants (PVs) in BRCA1 or BRCA2, where BRCA1 PVs are associated with a 39–63% lifetime risk of ovarian cancer and BRCA2 PVs are associated with a 15–27% risk." (PMID 33926482, 2021). "Given that any additional gene identified is likely to have lower penetrance than BRCA1 or BRCA2 e.g., in a large family with multiple breast/ovarian cancer cases (MS ≥ 40), it is unlikely that this will be the entire explanation for the pattern observed." (PMID 34439310, 2021). "To date, no studies have applied a wholly unbiased WES-based approach to ovarian carcinoma predisposition gene discovery in a case cohort selected for HGSOC and enriched for hereditary cases where BRCA1 and BRCA2 involvement have been excluded." (PMID 32242007, 2020). "Women carrying mutations in these genes have a lifetime risk of developing ovarian cancer of 36 to 60% for BRCA1 and 16 to 27% for BRCA2." (PMID 32316968, 2020). "The majority of ovarian cancers that develop in BRCA carriers (either BRCA1 or BRCA2) are high-grade serous ovarian carcinomas (HGSOC)." (PMID 32341426, 2020). "The cumulative risk of ovarian cancer in the BRCA1 and BRCA2 mutation carriers was 40% and 18%, respectively, at age 70, which was much higher than 1.4% in the general population." (PMID 32356124, 2020). "Ovarian cancer patients with deleterious variants in BRCA1 and BRCA2 are characterized by genomic instability within their tumours." (PMID 33086730, 2020). "Based on the best available evidence, variants in BRCA1, BRCA2, BRIP1, RAD51C, RAD51D, and the mismatch repair genes confer ovarian cancer risks that warrant the consideration of risk-reducing surgery." (PMID 33086730, 2020). "There is extensive information on the roles of BRCA1 and BRCA2 as tumour suppressor genes in ovarian cancer and this review will instead describe the available information on the other FA proteins involved in HR." (PMID 36046263, 2020).
ovarian carcinoma (continued). "Monoallelic mutations in five of these genes (BRCA1, BRCA2, PALB2, BRIP1 and RAD51C) increase the susceptibility to breast/ovarian cancer and are used in clinical diagnostics as bona-fide hereditary cancer genes." (PMID 32235514, 2020). "The cumulative lifetime risk for ovarian cancer is 44% (95% CI 36–53) for BRCA1 and 17% (95% CI 11–25) for BRCA2 mutation carriers." (PMID 32513307, 2020). "The 5–10% of breast/ovarian cancers (BC and OC) are inherited, and germline pathogenic (P) variants in DNA damage repair (DDR) genes BRCA1 and BRCA2 explain only 10–20% of these cases." (PMID 32957588, 2020). "Ovarian cancer patients whose tumors have a positive GIS Status and/or pathogenic variants in BRCA1 or BRCA2 are considered good candidates for treatment." (PMID 32403357, 2020). "Similar models using Australian oncologists to provide BRCA1 and BRCA2 genetic testing, and Canadian surgeons to provide genetic testing in ovarian cancer patient populations have also been reported." (PMID 32028617, 2020). "It was reported that 8.9% and 3.0% of ovarian cancer have BRCA1 and BRCA2 somatic variants, respectively." (PMID 32813918, 2020). "PARP inhibitors are effective in ovarian cancers with homologous recombination deficiency (HRD), 40% of which are attributed to BRCA1/BRCA2 germline or somatic variants." (PMID 32813918, 2020). "This study is the first report about the landscape of germline BRCA1 and BRCA2 PVs in a large cohort of patients affected by breast and ovarian cancer coming from the Central–South Italy." (PMID 32438681, 2020). "The cumulative risks for ovarian cancer by age 70 years were estimated to be 59% for BRCA1 carriers and 17% for BRCA2 carriers, and germline BRCA1 and BRCA2 mutations were exclusively associated with high-grade serous histology." (PMID 32098383, 2020). "We tested the association of RAD52 S346X with risk of developing breast or ovarian cancer in a large cohort of BRCA1 and BRCA2 mutation carriers." (PMID 32175645, 2020). "The French guidelines by INCa recommend annual clinical pelvic examination as screening for ovarian cancer in BRCA1 and BRCA2 mutation carriers." (PMID 32655641, 2020). "Women with inherited mutations in BRCA1 or BRCA2 had an increased risk of ovarian cancer, and for BRCA1 or BRCA2 mutation carriers, the lifetime risk of ovarian cancer were 54% and 23%, respectively." (PMID 32096544, 2020). "The downregulation of BRCA2 reduces the expression of the homologous recombination (HR) pathway-associated RAD51 protein and suppresses DNA repair in ovarian cancer cells, sensitizing them to cisplatin." (PMID 32404140, 2020). "In Spain, the accumulated risk of developing ovarian cancer before age 70 has been estimated at 22% (95% CI, 0–40%) in carriers of a mutation in BCRA1 and 18% (95% CI, 0–35%) in carriers of a mutation in BRCA2." (PMID 32807139, 2020). "The NOVA trial showed that niraparib was effective in patients with platinum-sensitive ovarian cancer, demonstrating that PARP inhibitors are effective in carriers of mutations other than BRCA1 and BRCA2." (PMID 32679669, 2020). "In the context of patients with known mutations in BRCA1 or BRCA2, the phase II basket study (MEDIOLA) evaluated combination of durvalumab (anti-PD-L1) and olaparib in 32 patients with platinum-sensitive relapsed ovarian cancer." (PMID 32457830, 2020). "A meta-analysis confirmed significantly reduced risk for ovarian cancer for BRCA1 (SRR = 0.51; 95% CI 0.40–0.65) and BRCA2 mutations carriers (SRR = 0.50; 95% CI 0.29–0.89) associated with use of OC." (PMID 32140806, 2020). "Both BRCA2 and STARD13 are well known tumor-suppressors, and upregulation of N4BP2L1 and N4BP2L2 has been associated with positive prognosis in ovarian cancer cases." (PMID 32404140, 2020). "The CIMBA retrospective cohort consisted of 18,935 BRCA1 carriers (9473 diagnosed with breast and 2068 with ovarian cancer) and 12,339 BRCA2 carriers (6332 with breast and 718 with ovarian cancer)." (PMID 32665703, 2020).
ovarian carcinoma (continued). "A genetic predisposition is thought to account for 5 to 10% of ovarian cancers, mainly through alterations of the BRCA1 gene, and more rarely, the BRCA2 gene." (PMID 32650744, 2020). "It has been reported that the average cumulative risks in BRCA1-mutation carriers by age of 70 were 65% and 39% for breast and ovarian cancers respectively and the corresponding estimates for BRCA2 were 45% and 11%." (PMID 33240314, 2020). "Germline pathogenic single nucleotide variations (SNVs) and small indels of the BRCA1 and BRCA2 genes are well-studied genetic changes in hereditary breast and ovarian cancers." (PMID 32629901, 2020). "Here, we describe two cases of DH in BRCA1/BRCA2 genes and three cases of DM in the BRCA2 gene in five probands with breast and ovarian cancer and in their families." (PMID 33287145, 2020). "One of the most well-known examples is that, a large fraction of hereditary breast cancer, ovarian cancer, and prostate cancer, which are accounted for by BRCA1 and BRCA2 mutations, which are pivotal genes in HR150." (PMID 33299637, 2020). "Our study is the first comprehensive report of LGRs of BRCA1 and BRCA2 genes in Hungarian familial breast and ovarian cancer patients and the largest survey in the Middle and Eastern European region." (PMID 32629901, 2020). "For ovarian cancer, the cumulative cancer risk to age 80 years is estimated to be 44% (95% CI = 36–53%) and 17% (95% CI = 11–25%) for BRCA1 and BRCA2 pathogenic variant carriers, respectively." (PMID 32772980, 2020). "It is estimated that more than 20% of ovarian cancer cases are associated with a genetic predisposition that is only partially explained by germline mutations in the BRCA1 and BRCA2 genes." (PMID 32359370, 2020). "For ovarian cancer, cumulative risk at age 80 years was estimated to 44% for BRCA1 carriers and 17% for BRCA2 carriers." (PMID 32025337, 2020). "Ovarian cancer incidence increases slowly from approximately 35 years onwards in patients with BRCA1-and from around 50 years onwards in BRCA2-mutations." (PMID 32655641, 2020). "The largest study included 1 ovarian cancer case with BRCA1 and 2 mutation, 670 ovarian cancer cases and 2043 controls with BRCA1 mutation as well as 128 cases and 380 controls with BRCA2 mutation." (PMID 32140806, 2020). "A large proportion of breast and ovarian cancer predisposition remains unexplained: analysis of genes other than BRCA1 and BRCA2 is needed." (PMID 32756499, 2020). "Recent clinical trials showed that PARP inhibitors and platinum are effective in treating ovarian cancer patients with mutations of BRCA1, BRCA2, and other genes encoding proteins involved in HR32." (PMID 32457312, 2020). "In a meta-analysis of published studies, the estimated mean cumulative risk for breast and ovarian cancers by 70 years of age for BRCA1 mutation carriers were 57% and 40%, respectively, while carriers of BRCA2 mutation had a risk of 49% and 18%, respectively." (PMID 32733560, 2020). "Some of these downstream FA genes are known as tumor suppressor genes in other monoallelic inherited cancers like breast and ovarian cancer (FANCD1 = BRCA2, FANCS = BRCA1, FANCN = PABLB2, FANCJ = BRIP1, FANCO = RAD51C)." (PMID 32397406, 2020). "We investigated the association of the RAD52 S346X variant as a modifier of the risk of developing breast and ovarian cancers in BRCA1 and BRCA2 mutation carriers from the Consortium of Investigators of Modifiers of BRCA1/2." (PMID 32175645, 2020). "Early studies of cases selected for a family history of breast or ovarian cancer found that 24–76% had deleterious variants in BRCA1 and 1–17% had deleterious variants in BRCA2." (PMID 33086730, 2020). "To date, twenty variants in BRCA1, BRCA2, and PALB2 that predispose families to breast and ovarian cancer have been identified as recurring in the French-Canadian founder population." (PMID 32300229, 2020).
ovarian carcinoma (continued). "It has been observed in multiple individuals with breast and/or ovarian cancer (also denoted BRCA2 9522C>G in the literature) and has been classified pathogenic by ENIGMA-consortium in the ClinVar and BRCA Exchange databases." (PMID 32468491, 2020). "For ovarian cancer, the PRS developed for predicting overall or HGS EOC demonstrated similar evidence of association with EOC risk, for both BRCA1 and BRCA2 carriers." (PMID 32665703, 2020). "While the association of BRCA2 and LUSC is first described in African-American ancestry here, BRCA2 was previously found to be associated with non-small cell lung cancer (including LUAD and LUSC) and ovarian cancer (OV) in the European ancestry." (PMID 32471518, 2020). "We assessed the associations between population-based polygenic risk scores (PRS) for breast (BC) or epithelial ovarian cancer (EOC) with cancer risks for BRCA1 and BRCA2 pathogenic variant carriers." (PMID 32665703, 2020). "It is known that approximately 10–15% of ovarian cancer patients harbor a germline mutation in genes encoding BRCA1 and BRCA2 proteins, which are involved in the process of homologous recombination (HR) that mediates repair of double stranded DNA breaks." (PMID 31898520, 2020). "Association of RAD52 S346X and risk of developing breast or ovarian cancer for BRCA1 and BRCA2 carriers." (PMID 32175645, 2020). "For example, Aurora-A suppresses BRCA2-expressing ovarian cancer cells while its silencing restores the level of BRCA2 and increases the number of DNA repair foci of both BRCA2 and Rad51 after γ-irradiation." (PMID 32550913, 2020). "Between 10% and 15% of women with EOC are genetically predisposed to ovarian cancer, and 90% have a BRCA mutation (BRCA1 or BRCA2)." (PMID 32679669, 2020). "Optimum timing of RRSO should take into account reported age-specific incidences of ovarian cancer among BRCA1 and BRCA2 mutation carriers." (PMID 31948486, 2020). "The cumulative risk to the age of 80 years for ovarian cancer is elevated up to 44% in BRCA1 and up to 17% in BRCA2 mutation carriers." (PMID 32719921, 2020). "This allowed them to investigate its impact on breast and ovarian cancer risk in individuals carrying pathogenic BRCA1 and BRCA2 mutation." (PMID 32255263, 2020). "This relationship between genotype and responsiveness to platinum chemotherapy was also observed among BRCA2 patients with breast and ovarian cancers." (PMID 33255593, 2020). "Inherited predisposition to acquire PCa is genetically determined by the presence of a deleterious mutation of DNA repair genes also related to breast/ovarian cancers (i.e., BRCA1 and BRCA2, ATM, etc.)or PCa-specific risk genes (HOXB13 and 8q24 region)." (PMID 33255593, 2020). "Single nucleotide polymorphisms (SNPs) in DNA glycosylase genes involved in the base excision repair (BER) pathway can modify breast and ovarian cancer risk in BRCA1 and BRCA2 mutation carriers." (PMID 30747491, 2019). "In this study cohort of 253 women, 213 had BRCA1 variants and only 40 had BRCA2 variants, which affects the generalizability as BRCA1 is associated with a higher risk of both breast and ovarian cancer." (PMID 31888263, 2019). "By the age of 80, the cumulative risks of breastand ovarian cancer increase, respectively, to 72% and 44% for BRCA1carriers, and 69% and 17% for BRCA2 carriers." (PMID 31067289, 2019). "This is comparable to high risk populations identified through genetic testing; the lifetime risk for ovarian cancer increases 27 and 11 times with BRCA1 and BRCA2 mutations, respectively." (PMID 33693347, 2019). "The mutation of some genes has also been associated with an increased risk of epithelial ovarian cancer, such as BRCA1 and BRCA2, BRIP1, RAD51C and RAD51D." (PMID 31182132, 2019). "BRCA1 and BRCA2 were first discovered in 1994 and 1995, and to date are the genes that have the strongest influence with ovarian cancer incidence." (PMID 30362670, 2019).